CXCL11 (C-X-C motif chemokine ligand 11)
Diseases named in the same sentence as CXCL11 in open-access papers (continued):
Sharing a sentence is not in itself a finding about the gene and the disease.
autoimmune disease (continued). "Among the large chemokine and chemokine receptor families, CXCR3 and CXCR3-binding chemokines CXCL10 and CXCL9 and ITAC/CXCL11 are key players in the maintenance and amplification of the autoimmune disease." (PMID 26892362, 2016). "A combination of four different proteins: BDNF (Brain Derived Neurotrophic Factor), I-TAC/CXCL11, soluble (s) CD163 and Fractalkine/CX3CL1 was identified as a pSS protein signature as it could discern pSS from other autoimmune diseases." (PMID 35892673, 2022). "Furthermore, CXCL11 levels can predict CD4+ T-cell count, with increased levels detected in mixed cryoglobulinemia, Graves’ disease, and some autoimmune diseases." (PMID 31836011, 2019).
lung carcinoma (18 papers, 2019 to 2025). "Regarding CXCL11, its expression was positively correlated with prolonged overall survival in lung cancer and colon adenocarcinoma patients." (PMID 36578780, 2022). "Even CCL19, transcribed by fibroblasts, inhibits the growth of lung cancer by promoting local anti-tumor T cell response and CXCL11 is known to be used as an enhancer of vaccine-induced CD8+ T cellular immunity." (PMID 34283076, 2021). "Tumor infiltrated CD8+ T cells are increased in lung cancer patients after DOC therapy, identifying the activation of apoptosis and the release of HMGB1 and CXCL11 as key events underpinning lung carcinoma cells-elicited leukocyte attraction." (PMID 30744691, 2019). "Increased HMGB1 and CXCL11 expressions were positively correlated with prolonged overall survival of lung cancer patients." (PMID 30744691, 2019). "Furthermore, CXCL11 has been established as an independent prognostic biomarker promoting anti-tumor immunity and prolonged overall survival in lung carcinoma patients." (PMID 38228372, 2024). "CXCL10 and CXCL11 may also be useful diagnostic biomarkers in early-stage NSCLC, while CXCL8 levels may be a useful predictor of future lung cancer risk." (PMID 36164329, 2022). "A study found that docetaxel induced CD8+ T cell recruitment into the tumor microenvironment by enhancing the secretion of CXCL11, thus improving antitumor efficacy, and that increased CXCL11 expression was positively correlated with prolonged OS in lung cancer patients." (PMID 35905218, 2022). "Runx3 knockdown can induce the downregulation of CXCL11 in lung cancer cells." (PMID 31708740, 2019). "Here, we evaluated the clinical implications and prognostic significance of IFN-γ-inducible chemokines by measuring levels of CXCL9, CXCL10, and CXCL11 and their inducer IFN-γ in the peripheral blood of patients with lung cancer." (PMID 34501934, 2021). "Again, many of the immune-modulatory genes differentially expressed in the mouse model were site-specifically recapitulated, e.g., higher CCL2, CXCL5, CXCL9, CXCL11, CXCL14, CXCL17, and IDO1 in lung cancers and higher CXCL12, FGL1, and LAG3 in liver cancers." (PMID 33985562, 2021). "The serum levels of IFN-γ were not correlated with the serum levels of CXL9, CXCL10, and CXCL11, respectively, in all lung cancer and NSCLC patients." (PMID 34501934, 2021). "Enhancement of paracrine CXCR3 ligands (CXCL9, CXCL-10, and CXCL-11) in the tumor microenvironment and deactivation of CXCR3 expression on cancer cells could be antitumorigenic by recruiting activated natural killer cells and T lymphocytes with potent antitumor effects in various lung cancer models." (PMID 36164329, 2022).
pancreatic cancer (18 papers, 2011 to 2025). "CXCL10 and CXCL11 were highly expressed in pancreatic cancer and associated with poor prognosis of patients through cell adhesion molecules chemokine signaling, cytokine-cytokine receptor interaction, natural killer cell-mediated cytotoxicity, and Toll-like receptor signaling pathways." (PMID 40129606, 2025). "For further validation, we used GEPIA and GEO databases (GES71729) to verify the expression of CXCL10 and CXCL11 in pancreatic cancer and their relationship with the prognosis of patients." (PMID 40129606, 2025). "Subsequently, we evaluated the DEGs related to the immune score and the stromal score and determined the prognosis-related genes from the clinicopathological data, and we identified CXCL10 and CXCL11 as prognostic factors in the pancreatic cancer TME." (PMID 40129606, 2025). "The results showed that the expression of CXCL10 and CXCL11 was significantly increased in pancreatic cancer, and CXCL10 was statistically significant." (PMID 40129606, 2025). "Nevertheless, our research confirmed that CXCL10 and CXCL11 are important genes for the prognostic evaluation of pancreatic cancer." (PMID 40129606, 2025). "In summary, we have identified CXCL10 and CXCL11 as key genes affecting the prognosis and immune infiltration of pancreatic cancer." (PMID 40129606, 2025). "Most importantly, the GEO databases (GES71729), GEPIA, TISIDB, TIMER databases PAAD cohort were used to verify our results, the expression levels of CXCL10 and CXCL11 in pancreatic cancer and normal pancreatic epithelial cells were verified by RT-PCR." (PMID 40129606, 2025). "CXCL9, CXCL10 and CXCL11 have been previously shown to be effective in supporting an adequate antitumoral response in various cancers, although results in pancreatic cancer have been conflicting." (PMID 39885986, 2024). "For example, a study noted that CXCL11 enhanced cancer proliferation and metastasis in pancreatic cancer." (PMID 37627528, 2023). "Furthermore, the research on CXCL11 in pancreatic cancer is still in the initial stage, related studies have only shown that CXCL11 is highly expressed in the serum of patients with pancreatic cancer and has a protumor function." (PMID 40129606, 2025). "Our findings indicate that CXCL10 and CXCL11 may be new targets for pancreatic cancer immunotherapy." (PMID 40129606, 2025). "CXCL10 and CXCL11 may be new targets for molecular targeted therapy and immunotherapy of pancreatic cancer." (PMID 40129606, 2025). "Recent studies have explored the role of CXCL10 and CXCL11 in pancreatic cancer." (PMID 40129606, 2025). "In addition, we revealed the relationship of CXCL10 and CXCL11 in immune cell infiltration landscape of pancreatic cancer." (PMID 40129606, 2025). "Finally, the molecular mechanism by which CXCL10 and CXCL11 are involved in immune cell infiltration in pancreatic cancer was analyzed, and these results are anticipated to facilitate pancreatic cancer immunotherapy." (PMID 40129606, 2025). "Most importantly, our study explored the mechanism of action of CXCL10 and CXCL11 in the TME and immune cell infiltration of PAAD and provided information anticipated to facilitate pancreatic cancer immunotherapy." (PMID 40129606, 2025). "Our study demonstrates that CXCL10 and CXCL11 are novel biomarkers of TME and immune cell infiltration in pancreatic cancer by affecting the distribution of immune cells." (PMID 40129606, 2025). "To further explore the important role of CXCL10 and CXCL11 in pancreatic cancer, we analyzed the related signaling pathways involving CXCL10 and CXCL11 through GSEA." (PMID 40129606, 2025). "The results of the PPI network and Cox regression analyses showed that CXCL10 and CXCL11 are valuable factors involved in the TME of pancreatic cancer and are correlated with the prognosis and clinicopathological characteristics of pancreatic cancer patients." (PMID 40129606, 2025).
pancreatic cancer (continued). "The experimental results showed that the mRNA expression levels of EMP1, GIPR, SFRP1, CXCL11 and COL17A were significantly high in the pancreatic cancer cell line compared with the controls." (PMID 37547756, 2023). "ONCOMINE data showed that in addition to CXCL1, CXCL4, CXCL11 and CXCL12, the mRNA levels of the other 12 CXC chemokines were significantly increased in pancreatic cancer." (PMID 35468838, 2022). "According to the previous study, FYN, LRSAM1, and SEMA6C serve as poor prognostic biomarkers in pancreatic cancer, whereas ERAP2, MET, IL20RB, and CXCL11 indicate improvements." (PMID 36428747, 2022). "The CXC ligand family (CXCL5, CXCL9, CXCL10, CXCL11, and CXCL17) plays a vital role in regulating pancreatic cancer progression." (PMID 33393862, 2021). "Other members of the C-X-C motif chemokine family were found to be upregulated in pancreatic cancer cells after Rintatolimod treatment, like CXCL 1, CXCL2, CXCL3, CXCL8 (IL-8), CXCL11, CXCL14, and CXCL16." (PMID 34207861, 2021). "Next, we observed consistent increases in ERK1/2 phosphorylation after exposure to CXCL12 or CXCL11, a CXCR7 agonist, in pancreatic cancer cell lines co-expressing CXCR4/CXCR7." (PMID 22472349, 2012). "To determine if CXCL12 exposure results in changes in pancreatic cancer cell proliferation, we exposed cells to CXCL12 and CXCL11 for 72 h." (PMID 22472349, 2012). "Binding of CXCL12 or interferon-inducible T-cell alpha chemoattractant (I-TAC/CXCL11), the other known CXCR7 ligand, to CXCR7 activates PI3K and MAPK signaling in astrocytes, Schwann cells, gliomas, rhabdomyosarcoma, and pancreatic cancer cells." (PMID 22152016, 2011). "Our data also suggest that the ligands for the chemokine receptors CXCR3 (CXCL9, CXCL10, CXCL11) and CCR5 (CCL8) might affect the spatial distribution of CD8+ T cells in human pancreatic tumor tissues and enhance the relative T cell trafficking into tumor rich areas." (PMID 35954489, 2022).
gastric cancer (13 papers, 2012 to 2025). A primary or metastatic malignant neoplasm involving the stomach. "APSN+CXCL11+APOE+ fibroblasts were found to be associated with gastric cancer (GC) development." (PMID 39905493, 2025). "RHOA mutated gastric cancer cells reduced the secretion of CXCL10 and CXCL11, and stimulated the synthesis of fatty acids through the PI3K-AKT-mTOR pathway, which in turn enhances the inhibition of regulatory T cells (Tregs) within the TIME, thereby inducing immunosuppression." (PMID 40149008, 2025). "Chemokine gene expression signatures including CCL5, CXCL9, CXCL10, and CXCL11 were reported that could accurately predict anti-PD-1 immunotherapy response for patients with head and neck squamous cell carcinoma and gastric cancer." (PMID 32316408, 2020). "In the comparison of metabolite interference group and M1 group marker proteins in gastric cancer cells, there were significant differences in IL-6, CXCL9, CXCL10 and CXCL11." (PMID 39991579, 2025). "ROC analysis identified genes with high specificity and sensitivity for discriminating EBV+ gastric cancer, including GBP5, CMKLR1, GM2A and CXCL11 that play pivotal roles in immune response, inflammation, and cancer." (PMID 40110195, 2025). "CXCL9, CXCL10 and CXCL11 have especially been considered as IFN-γ response cytokines and have been reported to modulate the expression of PDL-1 in gastric cancer cells." (PMID 36766722, 2023). "This discovery was consistent with the finding that PD-L1 is upregulated after treatment with CXCL11, accompanied by activation of STAT3 and Akt in gastric cancer." (PMID 33777950, 2021). "Examples include the high expression of LOC100506114 enhancing GDF10 secretion to promote oral squamous cell carcinoma metastasis, LINC00152 enhancing CXCL-11 secretion to promote liver cancer metastasis, and NORAD enhancing IL-33 secretion to promote gastric cancer metastasis." (PMID 39717771, 2024). "Nine human RNAs were significantly upregulated in EBV-infected compared to EBV negative gastric cancers: FCER2, MS4A1 (CD20), PLUNC, TNFSF9, TRAF1, CXCL11, IFITM1, PPARG, and FCRL3.." (PMID 22929309, 2012).
influenza (13 papers, 2014 to 2025). An acute viral infection of the respiratory tract, occurring in isolated cases, in epidemics, or in pandemics; it is caused by serologically different strains of viruses (influenzaviruses) designated A, B, and C, has a 3-day incubation period, and usually lasts for 3 to 10 days. "CXCR3 ligands CXCL9, CXCL10 and CXCL11 are highly expressed in the lung in response to influenza as well as M. tuberculosis infection." (PMID 37896952, 2023). "Notably, CXCL10, CXCL9, and CXCL11 had previously been found to be upregulated in human nasal epithelial cells after infection with human influenza H3N2." (PMID 41239423, 2025). "All but six of these proteins (CCL11, CXCL11, IFNγ, MCP-2, SCF, and TRAIL) were significantly less expressed in patients with influenza." (PMID 35264246, 2022). "Neutrophils isolated from influenza-infected mouse lungs were stimulated with CCR1, CCR5, CXCR2, and CXCR3 specific ligands CCL3, CCL4, IL-8, and CXCL11 (100 ng/mL), respectively, and incubated for 4 h." (PMID 31041196, 2019). "By day 7, expression of Ccl3, Cxcl9, Cd86, Il-6, Cd80, and Cxcl11 remained elevated in young adult lung in response to H1N1, while expression of Ccl5, Ccl4, and Cd40 remained elevated in response to either strain of influenza." (PMID 34829979, 2021). "Neutrophils isolated from influenza-infected mouse lungs were stimulated with CCR1, CCR5, CXCR2, and CXCR3 specific ligands including CCL3, CCL4, IL-8, and CXCL11 (100 ng/mL) for 20 min, followed by incubation with a 1:10 ratio of Streptococcus pneumoniae (serotype 3) for 90 min." (PMID 31041196, 2019). "Influenza infection also induces the production of such cytokines as TNFa, IL-1, IL-6, and the mononuclear cell attractant chemokines: CCL-3, CCL-4, CCL-5, CXCL9, CXCL10, and CXCL11 in human monocytes, epithelial cells, and rat alveolar or murine macrophages." (PMID 30037133, 2018).
colitis (12 papers, 2008 to 2025). Inflammation of the colon. "Together, the data show that Mycobacteria-dependent host responses, namely CXCL10+ T cells and NK cells, assist in the recruitment and activation of CXCR3+ and CXCL11+ leukocytes to enhance colitis of susceptible hosts." (PMID 18533024, 2008). "Both CCL5 and CXCL11 are satisfactory therapeutic molecule candidates to test initially on animal colitis models." (PMID 30037025, 2018). "This makes the administration of exogenous CXCL11 a satisfactory therapeutic possibility to test on animal colitis models." (PMID 30037025, 2018). "As with these innate immunity cells, neutrophils are compartmentalized in the MLN and tightly regulated to differentially express CXCL9 and CXCL11, CXCR3 and Th1-associated cytokines during Mycobacteria-mediated colitis." (PMID 18533024, 2008). "In contrast, we noticed a modest decrease in the number of PP CXCR3+, IFN-γ+, CXCL9+ and CXCL11+ NK cells during live Mycobacteria-enhanced colitis." (PMID 18533024, 2008). "CXCR3 interactions with CXCL9, CXCL10 and CXCL11 are important for the selective homing of Th1 effectors cells, which mediate mucosal immunity, inflammation, and colitis." (PMID 18533024, 2008). "However, after 7 days of colitis induction, the gene expression of Cxcl11 was lower in the CβGl+ group." (PMID 35163326, 2022). "After 7 days of induced colitis, upregulation of the expression of 22 genes (Ccl2, Ccl3, Ccl4, Ccl5, Ccl6, Ccl7, Ccl12, Ccl17, Cxcl1, Cxcl2, Cxcl6, Cxcl9, Cxcl11, Ccr1, Ccr2, Ccr3, Ccr5, Ccr8, Cxcr2, Csf3, Osm, and Spp1) was observed in the CβG− group compared to the HβG- control group." (PMID 35163326, 2022). "Furthermore, the gene expression of Cxcl11 in the colitis group consuming feed with beta-glucan (βGl+) was higher compared to the control group (HβG−) at both time points." (PMID 35163326, 2022). "Interestingly, our data clearly showed that administration of IL-17A attenuated the ability of CECs from TNBS-induced colitis mice to induce colitis when transferred into recipients and decreased the expression of CXCL11, IL-12P35, and IFN-γ." (PMID 24586980, 2014). "In addition, we blocked IL-17A in mice with TNBS- induced colitis in vivo and found that this enhanced CXCL11 and IL-12P35 mRNA expression by CECs." (PMID 24586980, 2014). "The numbers of MLN and LP DCs subsets expressing CXCL9 and CXCL11 after the onset of colitis were significantly increased during live Mycobacteria-enhanced colitis than in the other groups with the exception of MLN CXCL10+ myeloid DCs that were elevated following live bacterial challenge." (PMID 18533024, 2008). "This is partly evidenced by an elevated expression of T-cell chemoattractants such as CXCL9, CXCL11, and CCL21 in colonic epithelial cells in piglets with DSS-induced colitis." (PMID 35898495, 2022). "Our analysis resulted in identifying three new therapeutic targets towards ameliorating colitis: CCL5, CXCL11, and CCL17." (PMID 30037025, 2018). "While CCL5 and CXCL11 are good therapeutic chemokine candidates to be exogenously administered, CCL17 is a good candidate chemokine to competitively inhibit or limit colitis pathology." (PMID 30037025, 2018). "Adoptively transferred CECs from TNBS-induced colitis mice exacerbated tissue damage and led to increased mRNA expression of CXCL11, IL-12P35, and IFN-γmRNA by CECs of the recipient mice of TNBS colitis mice." (PMID 24586980, 2014). "Our results also suggest plasmacytoid > > myeloid DCs express CXCL9 and CXCL11, but less CXCL10 as well as IFN-γ to recruit, differentiate, and expand Th1 cells to mediate colitis." (PMID 18533024, 2008). "PP and MLN DCs expressed elevated levels of CXCL9 and CXCL11, but not CXCL10, during Mycobacteria-enhanced colitis as indicated by their relative mean fluorescent intensities." (PMID 18533024, 2008).
hepatocellular carcinoma (12 papers, 2016 to 2026). A malignant tumor that arises from hepatocytes. "CXCL11 has been reported to be up-regulated in hepatocellular carcinoma (HCC) tissues and cancer-associated fibroblasts (CAFs), and CAF-secreted CXCL11 has been found to promote HCC cell proliferation and migration." (PMID 36435866, 2022). "Both the receptor and CXCL11 are present at higher levels in hepatocellular carcinoma (HCC) than in healthy livers in both mice and humans." (PMID 32098047, 2020). "In hepatocellular carcinoma, the level of CXCL11 secreted by CAFs was considerably elevated compared with that of normal fibroblasts, and CXCL11 stimulated the upregulation of circUBAP2 expression, which further indirectly affected the levels of IL-17 and IL-1β by inhibiting miR-4756 expression." (PMID 40109856, 2025). "In this study, CXCL11 signaling through CXCR3 led hepatocellular carcinoma cells to acquire and maintain properties like self-renewal, tumorigenicity, and chemoresistance via activation of the ERK1/2 pathway, and CXCL11 knock-down reduced tumorgenicity in a mouse xenograft model." (PMID 36118530, 2022). "Furthermore, the CXCR3 ligand CXCL11 was upregulated in hepatocellular carcinoma MICs and induced the expression of stem cell-related genes, including NANOG." (PMID 36118530, 2022). "For example, UHRF1 in hepatocellular carcinoma (HCC) 19, CXCL11 in colorectal cancer (CRC) 20, AFF3 in GC 21, and so on." (PMID 38706903, 2024). "We newly found that proinflammatory IL-17+ cells in the peritumoral stroma stimulated hepatoma cells to produce CXCL9, CXCL10 and CXCL11, which in turn led to CXCR3+ B-cell recruitment, maturation and IgG production." (PMID 27853178, 2016).